GRHL2 (grainyhead like transcription factor 2)
Diseases named in the same sentence as GRHL2 in open-access papers (continued):
Sharing a sentence is not in itself a finding about the gene and the disease.
ectodermal dysplasia (5 papers, 2014 to 2023). "We have used whole-exome sequencing to identify GRHL2 mutations underlying an ectodermal dysplasia syndrome in two families, and our data expand the current knowledge about the role of GRHL2 in human disease and epithelial cell biology." (PMID 25152456, 2014). "None of the PPCD-affected individuals with GRHL2 promoter mutations in our study reported hearing loss or other features of ectodermal dysplasia syndrome." (PMID 29499165, 2018). "In this report, however, we have identified two families in which affected subjects have developmental defects affecting skin, oral mucosa, and teeth (as well as hearing and lungs), thus implicating GRHL2 in an autosomal-recessive ectodermal dysplasia syndrome." (PMID 25152456, 2014).
oral squamous cell carcinoma (5 papers, 2011 to 2024). "Furthermore, the oncogenic role of GRHL2 is observed in hepatocellular carcinoma, esophageal cancer, oral squamous cell carcinoma, and colorectal carcinoma." (PMID 32974388, 2020). "Furthermore, GRHL2 has been shown to promote the initiation of oral squamous cell carcinoma." (PMID 39402063, 2024). "In cultured oral squamous cell carcinoma (OSCC) cell lines, TGF-β signaling was notably induced by GRHL2 knockdown while being suppressed by GRHL2 overexpression." (PMID 29735981, 2018). "In addition, the study also identifies that GRHL2 mediated activation of MAP kinase signaling and repression of TGF-β signaling in oral squamous cell carcinoma cell lines, dually render tumor promoting effects during the early stages of carcinogenesis." (PMID 32974388, 2020).
breast tumors (4 papers, 2013 to 2024). "Clinical data gathered from patients with ER-positive breast cancer not only reveal increased GRHL2 in breast tumors compared to normal tissues, but emphasize an association between high levels of GRHL2 expression and reduced disease-free survival." (PMID 39199676, 2024). "Functional downregulation of GRHL2 is known to be associated with elevated cell proliferation; yet, its protein expression has been found to be downregulated at the invasion front of primary breast tumors." (PMID 29287594, 2017).
hepatocellular carcinoma (4 papers, 2016 to 2022). A malignant tumor that arises from hepatocytes. "Of the GRHL1-3 factors, GRHL2 acts as an oncogene in hepatocellular carcinoma (HCC) and HCC cells show decreased proliferation following GRHL2 downregulation." (PMID 35269877, 2022).
oral cancer (4 papers, 2018 to 2020). "Conditional deletion of Grhl2 prevents oral cancer development in a chronic, chemically induced carcinogen model, when compared to the aggressive tumor formation in Grhl2 wild-type mice." (PMID 32974388, 2020). "GRHL2 was found to stimulate MAPK signalling pathway in oral cancer development." (PMID 32324317, 2020). "Also, GRHL2 promotes miR‐200 expression by directly binding at the miR‐200 promoter region, which leads to oral cancer development." (PMID 32324317, 2020). "Our prior study showed the role of GRHL2 in established human oral cancers using in vitro models." (PMID 29735981, 2018). "Moreover, consistent with our study, MAPK was also found to be activated by GRHL2 in oral cancer." (PMID 32324317, 2020). "Hence, the data support the preventive and mitigative effects of Grhl2 KO on oral dysplastic lesions, and this finding raises the possibility that GRHL2 may be an effective target for oral cancers." (PMID 29735981, 2018).
pancreatic cancer (4 papers, 2017 to 2024). "Our collective findings suggest that miR-6794-3p regulates invasion and migration of pancreatic cancer cells through targeting the RBBP4/GRHL2 signaling pathway." (PMID 39430246, 2024). "Based on our collective results, we conclude that miR-6794-3p modulates tumor growth via regulation of RBBP4/GRHL2 signaling, and has considerable value as a potential biomarker of metastasis in pancreatic cancer." (PMID 39430246, 2024). "Subsequently, we investigated the effects of miR-6794-3p on GRHL2 expression in pancreatic cancer cells." (PMID 39430246, 2024). "We further investigated whether miR-6794-3p-mediated inhibition of RBBP4 expression enhances the GRHL2-induced increase in expression of epithelial markers and decrease in invasion and migration in pancreatic cancer cells." (PMID 39430246, 2024). "Accordingly, we examined whether miR-6794-3p regulates GRHL2-mediated pancreatic cancer cell invasion and migration through regulatory effects on RBBP4." (PMID 39430246, 2024). "Next, we determined whether miR-6794-3p-mediated inhibition of RBBP4 expression exerts a regulatory effect on GRHL2 in pancreatic cancer cells." (PMID 39430246, 2024). "To explore the signal cascade between miR-6794-3p and GRHL2 in pancreatic cancer cells, we transfected miR-Cont- or miR-6794-3p mimic-MIA-PaCa-2 cells and miR-Cont- or miR-6794-3p inhibitor-transfected HPAF-II cells with pCont or pGRHL2 and siCont or siGRHL2, respectively." (PMID 39430246, 2024). "We also investigated whether miR-6794-3p-inhibited RBBP4 signaling could regulate the invasion and migration of pancreatic cancer cells by modulating GRHL2 expression." (PMID 39430246, 2024). "However, in pancreatic cancer, the miRNAs that regulate GRHL2 and, in turn, tumor cell invasion and migration are currently unknown." (PMID 39430246, 2024). "The resulting suppression of RBBP4 induced an increase in the levels of GRHL2 involved in regulating invasion, migration, and EMT signaling in metastatic pancreatic cancer cells." (PMID 39430246, 2024).
spina bifida (4 papers, 2018 to 2023). A congenital neural tube defect in which vertebrae are not fully formed. "The molecular and cellular effects of Grhl2 over-expression are largely opposite to those of Grhl2 loss of function, yet remarkably also result in severe spina bifida." (PMID 31171776, 2019). "Spinal neural tube closure is highly sensitive to the abundance of Grhl2; with loss or over-expression of Grhl2, leading to spina bifida." (PMID 31171776, 2019). "Whether and how these surface ectoderm defects prevent cranial closure is still unknown, as is the causative mechanism underlying Grhl2-related spina bifida." (PMID 31171776, 2019). "Our initial analysis of the GRHL2 promoter region in individuals with spina bifida (the category of NTDs present in Grhl2Axd mice) or cleft palate revealed several rare SNVs." (PMID 37364051, 2023).
corneal endothelial dystrophies (3 papers, 2023 to 2024). "We also evaluated the possible pathogenicity of variants in genes known to be associated with congenital or childhood-onset monogenic corneal endothelial dystrophies (i.e., GRHL2, ZEB1, and OVOL2)." (PMID 40225920, 2024). "While the majority of GRHL2 mutations identified to date appear to result in diminished function, non-coding intronic variants that increase transcription in vitro have been identified in individuals with corneal endothelial dystrophy." (PMID 37364051, 2023).
liver cancer (3 papers, 2018 to 2021). An epithelial or non-epithelial malignant neoplasm that arises from the liver. "Furthermore, we performed RT-qPCR assays, which confirmed the expression of RNASE4 and GRHL2 in 30 pairs of liver cancer and adjacent tissues." (PMID 34235075, 2021). "Indeed, a combination of experimental data and mathematical modelling demonstrated that e.g. the transcription factor GRHL2 stabilizes the intermediate E/M state and predicts poor outcomes in breast, kidney, lung, and liver cancers." (PMID 29732000, 2018). "Immunohistochemistry was also performed in 10 paired of liver cancer and adjacent tissues to furthermore measure the expression of RNASE4 and GRHL2." (PMID 34235075, 2021).
metastatic tumors (3 papers, 2012 to 2022). "In our cohort, only a single splice variant in GRHL2 was identified, suggesting that its role in metastatic disease is limited." (PMID 35982973, 2022).
posterior polymorphous corneal dystrophy (3 papers, 2018 to 2023). Posterior polymorphous corneal dystrophy (PPCD) is a rare mild subtype of posterior corneal dystrophy characterized by small aggregates of apparent vesicles bordered by a gray haze at the level of Descemet membrane, generally with no effect on vision. "They show phenotypic overlap with posterior polymorphous corneal dystrophy (PPCD) caused by pathogenic variants in OVOL2, ZEB1, and GRHL2, but no genetic cause for PCVs has been identified, although an association with x-linked megalocornea was noted in one case." (PMID 36079096, 2022).
breast adenocarcinoma (2 papers, 2013 to 2024). "We next evaluated the correlation between GRHL2, CD73, and CD8 by IHC in a set of 10 GRHL2-high, 10 GRHL2-low (based on RNA-seq), and 10 metaplastic breast adenocarcinoma patient tumors." (PMID 38706844, 2024). "To confirm that Grhl2 contributes to increased metastatic potential in epithelial cells, we generated several stable GRHL2 overexpression (G+) clones for MCF7, a human breast adenocarcinoma cell line, and MDCK, a canine kidney cell line." (PMID 23441166, 2013).
Cirrhosis (2 papers, 2021 to 2025). A chronic disorder of the liver in which liver tissue becomes scarred and is partially replaced by regenerative nodules and fibrotic tissue resulting in loss of liver function. "Single-nuclei RNA-seq data analysis of human livers at different stages of MASLD showed increased GRHL2-expressing hepatocytes in end-stages of the disease (i.e., cirrhosis and liver failure) when compared to healthy control livers." (PMID 41385584, 2025). "To assess GRHL2 expression and its link to HCT in human livers, we first used samples from patients with ALD-related decompensated cirrhosis." (PMID 41385584, 2025).
CNS cancer (2 papers, 2023). "Surprisingly, we found that inducing GRHL2 in glioma stem cells (GSCs) altered cell-cycle drivers and promoted aneuploidy." (PMID 37761927, 2023). "To test this, we constructed GRHL2 dox-inducible glioma stem cells (GSCs) derived from a low-passage PDX sample." (PMID 37761927, 2023).
Colon Cancer (2 papers, 2020 to 2025). "Moreover, relatively high coexpression scores were also observed for FOSL2/KLF6, FOSL2/RUNX2 and GRHL2/FOXA1, suggesting that the DETFs related to H3K23su DERs might work together and be responsible for 5-FU resistance in HCT15 colon cancer cells." (PMID 40082673, 2025).
lung adenocarcinoma (2 papers, 2021 to 2023). A carcinoma that arises from the lung and is characterized by the presence of malignant glandular epithelial cells. "Through mathematical modeling and in vitro confirmation in lung adenocarcinoma cell lines, they identified grainyhead like transcription factor 2 (GRHL2) and microRNA 145 as additional factors responsible for the inhibition of complete EMT." (PMID 38009093, 2023). "On the other hand, the mother, also a carrier of the GRHL2 variant, was recently diagnosed with ALK-positive lung adenocarcinoma." (PMID 33810548, 2021).
non-small cell lung carcinoma (2 papers, 2018 to 2021). A group of at least three distinct histological types of lung cancer, including non-small cell squamous cell carcinoma, adenocarcinoma, and large cell carcinoma. "This is consistent with findings of the differential GRHL2 methylation between epithelial and mesenchymal cell lines in non small cell lung cancer." (PMID 30154364, 2018).
Obesity (2 papers, 2014 to 2025). Accumulation of substantial excess body fat. "Of them, Ctnnd2, Dap, Marchf6, Cmbl, Sdc2, Cpq, Stk3, Vps13b, Cox6c, Grhl2, Fzd6, Cthrc1, Lrp12, and Zfpm2 showed associations or had functions related to atherosclerosis or obesity." (PMID 40362477, 2025).
preeclampsia (2 papers, 2020 to 2021). Preeclampsia is a hypertensive disorder of pregnancy that is characterized by new-onset hypertension with proteinuria presenting after 20 weeks of gestation, and depending on mild or severe forms may initially present with severe headache, visual disturbances, and hyperreflexia. "It was reported that circTRNC18 is negatively regulated trophoblast cell migration and EMT via regulating miR-762/Grhl2 axis in preeclampsia; however, the role of circTRNC18 in GC is still unclear." (PMID 32462010, 2020). "CircTRNC18, a circRNA alias hsa_circ_0006772, which is transcripted from TNRC18 gene, was reported to negatively regulate trophoblast cell migration and EMT via regulating miR-762/Grhl2 axis in preeclampsia." (PMID 32462010, 2020). "In addition, showed that CircTRNC18 inhibits trophoblast cell migration and epithelial-mesenchymal transformation by regulating the miR-762/grainyhead like transcription factor 2 (GRHL2) pathway of preeclampsia." (PMID 33967782, 2021).
psoriasis (2 papers, 2019 to 2020). An autoimmune condition characterized by red, well-delineated plaques with silvery scales that are usually on the extensor surfaces and scalp. "The abnormal expression of GRHL2 in the psoriasis epidermis prevents the recruitment of demethylase JMJD3 to the EDC gene promoters and enhances the H3K27me3 level in gene promoter, thus causing cell hyperproliferation." (PMID 33011750, 2020).
alcoholic fatty liver (1 paper, 2020). "To better explore its underlying mechanism, we silenced GRHL2 in vivo to detect to detect liver function indicators, inflammatory factors, liver tissue changes, liver fibrosis and intestinal mucosal barrier dysfunction in non‐alcoholic fatty liver." (PMID 32324317, 2020).
bacteremia (1 paper, 2025). "Although no cases of liver abscess caused by Porphyromonas endodontalis have been reported, it may increase the risk of systemic bacteremia by targeting the GRHL2 and damaging the oral epithelial barrier." (PMID 40018345, 2025).
basal cell carcinoma (1 paper, 2024). A carcinoma involving the basal cells. "Currently, it remains unknown if the loss of GRHL2 expression is associated with aggressive cutaneous squamous cell carcinoma or basal cell carcinoma." (PMID 39402063, 2024).
cleft palate (1 paper, 2023). Cleft palate is a fissure type embryopathy that affects the soft and hard palate to varying degrees. "Initial analysis of the GRHL2 upstream region in individuals with NTDs or cleft palate revealed rare or novel variants in a small number of cases." (PMID 37364051, 2023). "Sequence variants identified in the GRHL2 upstream region in individuals with NTDs or cleft palate." (PMID 37364051, 2023). "Interestingly, the three individuals with cleft palate that carried the rarest variants also had other features that have been associated with GRHL2 mutation in humans or mice, including micrognathia, hearing and kidney anomalies." (PMID 37364051, 2023). "As a preliminary investigation of the potential contribution of GRHL2 upstream variants to orofacial clefts, we also screened this region for rare variants (minor allele frequency < 0.1%) in 397 individuals whose annotated clinical phenotype included ‘cleft palate’ from the 100,000 Genomes Project." (PMID 37364051, 2023). "However, an ENU-induced point mutation or diminished craniofacial expression of Grhl2 causes midline fusion defects and/or infrequent cleft palate, while knockout in the pharyngeal ectoderm causes occasional micrognathia suggesting a requirement in mandibular and maxillary development." (PMID 37364051, 2023). "Whether the variants identified in NTDs and cleft palate contribute to these anomalies is as yet unknown and, in the future, functional studies would be required to assess a potential impact of these variants on GRHL2 regulation." (PMID 37364051, 2023). "As an initial investigation of this possibility, we analyzed the upstream region of GRHL2 (2.5 kb 5′ upstream of exon 1) using WGS data of individuals with spinal NTDs or cleft palate." (PMID 37364051, 2023). "We therefore asked whether any of these features co-occurred with cleft palate among the individuals carrying rare SNVs in the GRHL2 upstream region and found one or more to be present in 5 of the 10 cases." (PMID 37364051, 2023). "Similarly, in the current study we found that cleft palate can occur among Grhl2Axd/+; Grhl3+/TgGrhl3 fetuses (one out of two) and Grhl3TgGrhl3/TgGrhl3 over-expressing fetuses (one out of four) at E15.5, showing that increased Grhl2 is unlikely to cause CL/P via suppression of GRHL3." (PMID 37364051, 2023).
colon adenocarcinoma (1 paper, 2021). "GRHL2 upregulation in the CTC lines prompted us to study its expression in more detail using microarray data (GEO accession number GSE41258) of primary colon adenocarcinoma, metastatic cancer, and the corresponding normal mucosa samples." (PMID 34771571, 2021).
cyst (1 paper, 2025). A sac-like closed membranous structure that may be empty or contain fluid or amorphous material. "In this context, GRHL2 induces epithelial genes such as genes involved in tight junctions and promotes acquisition of cyst-like structures." (PMID 41385584, 2025).
diabetes insipidus (1 paper, 2019). A disorder characterized by excretion of large amounts of urine, accompanied by excessive thirst. "Grhl2-deficient mice show signs of diabetes insipidus and fail to concentrate their urine adequately, although AQP-mediated water transport across the apical and basolateral membranes of Grhl2-deficient collecting ducts is intact." (PMID 31905642, 2019).
ductal carcinomas (1 paper, 2025). "Compared to lobular, ductal carcinomas (p = 0.005) and other types (p < 0.001) more frequently displayed a mixed GRHL2 immunostaining." (PMID 40889682, 2025). "A diffuse GRHL2 distribution was significantly less frequent in ductal carcinomas (p < 0.001) and other types (p < 0.001) than in lobular carcinomas." (PMID 40889682, 2025).
ectodermal dysplasia/short stature syndrome (1 paper, 2020). "For instance, GRHL2 (OMIM: 608576) known to cause recessive ectodermal dysplasia/short stature syndrome, which involves nail dystrophy, was correctly linked to Nail dystrophy with recessive MOI by Phenogenon (HGF score: 10.54)." (PMID 32271766, 2020).
Encephalocele (1 paper, 2023). A neural tube defect characterized by sac-like protrusions of the brain and the membranes that cover it through openings in the skull. "In summary, we find that Grhl2 overexpression causes multiple structural malformations in mice, and we propose that GRHL2 represents a candidate for involvement in human congenital anomalies including NTDs, encephalocele and CL/P." (PMID 37364051, 2023). "Furthermore, we identified the genomic lesion in Grhl2Axd/Axd embryos and therefore identified a shared genetic basis for orofacial clefts, encephalocele and spinal NTDs involving an insertional mutation that leads to dysregulation of Grhl2." (PMID 37364051, 2023). "Hence, in both Rac1 and Grhl2 models, encephalocele definitively arises after neural tube closure is complete." (PMID 37364051, 2023). "It is not yet known whether GRHL2 dysregulation is involved in human NTDs or encephalocele, both of which may co-occur with CL/P, suggesting a possible shared genetic etiology." (PMID 37364051, 2023).
epithelial dysplasia (1 paper, 2018). "When Grhl2 was knocked out 4 weeks into 4-NQO treatment (Tmx2), the epithelium developed multifocal mild to moderate epithelial dysplasia with a higher mitotic index." (PMID 29735981, 2018).
frontal encephalocele (1 paper, 2023). "As frontal encephalocele was readily identified by E17.5, we conducted Alcian Blue and Alizarin red staining at E18.5 on Grhl2+/+ and Grhl2Axd/Axd fetuses." (PMID 37364051, 2023).